VDR (vitamin D receptor)
Diseases named in the same sentence as VDR in open-access papers (continued):
Sharing a sentence is not in itself a finding about the gene and the disease.
autoimmune disease (continued). "Low levels of Vitamin D, together with genetic variations within the VDR gene, have been associated with susceptibility to different conditions, including neurodegenerative diseases, neurodevelopmental diseases, frailty in elders, and, particularly, autoimmune diseases." (PMID 37508347, 2023). "Therefore, reduced signal transduction due to polymorphic variants of the VDR gene might skew the immune response to the Th1 pathway that was implicated in the progress of organ-specific autoimmune diseases." (PMID 32727130, 2020). "Thus, the TaqI, BsmI, and ApaI polymorphisms of VDR gene are the most widely reported as being closely linked with a high risk of autoimmune diseases including PBC, multiple sclerosis (BsmI AA), Type 1 diabetes (TaqI T or BsmI AA), and systemic lupus erythematosus (BsmI AA)." (PMID 32727130, 2020). "Numerous polymorphisms of the VDR gene have been identified, some of them previously associated with different biological responses to vitamin D and suspected to play a role in the predisposition and development of several disorders, such as tumours, allergy, inflammation and autoimmune diseases." (PMID 33067526, 2020). "Vitamin D receptors (VDR) are expressed in immune cells, where they regulate proliferation and differentiation, thereby influencing the development of autoimmune diseases, including autoimmune thyroid disorders." (PMID 39911809, 2025). "The aim of this narrative review was to explore and discuss the possible role played by VDR and its four more widely investigated SNPs (ApaI, BsmI, TaqI, and FokI) in the pathogenesis of autoimmune diseases." (PMID 37508347, 2023). "This review aims to summarize the available information on the role of VDR methylation signatures in different pathological contexts, including autoimmune diseases, infectious diseases, cancer, and others." (PMID 38203278, 2023). "The table summarizes the principal results for VDR SNPs TaqI, BsmI, ApaI, and FokI SNPs involvement in autoimmune diseases." (PMID 37508347, 2023). "Because the vitamin D receptor is expressed in a variety of immune cell types, study into the precise role of this molecule in diseases, notably autoimmune disorders, has been made possible." (PMID 37520529, 2023). "We suggest designing future case-control studies taking into consideration only homogeneous populations from racial and ethnic points of view to better clarify the contribution of VDR SNPs to autoimmune diseases in different populations." (PMID 37508347, 2023). "Overall, the study on the role of VDR methylation pattern in autoimmune diseases still remains a controversial and under-explored area in current research." (PMID 38203278, 2023). "The search for the significance of this VDR promoter methylation pattern in MS patients, as well as in patients with other autoimmune diseases, is a challenge for further research." (PMID 36296970, 2022). "Apart from the VDR polymorphism, the authors highlighted the potential role of CYP27B1 polymorphisms with a favorable genetic background for various autoimmune disorders including T1DM." (PMID 36296970, 2022). "Albeit we know that VDR expression is reduced in the mucosal epithelial layers of autoimmune diseases, the mechanism by which VDR is decreased remains elusive." (PMID 34380509, 2021). "Previous investigations have suggested that VDR expression is compromised in the mucosal epithelial cells of autoimmune diseases such as OLP and IBD." (PMID 34380509, 2021). "Also, genetic variants in VDR gene, which codes for vitamin D receptor that regulates expression of more than 200 human genes, have been shown to increase susceptibility to acute lower respiratory infections in children, as well as several inflammatory and autoimmune diseases." (PMID 34150833, 2021).
autoimmune disease (continued). "Whilst vitamin D has minor effects on the myeloid methylome, age-dependent differences in VDR peak DNA methylation suggest vitamin D exposure at critical periods in immune system development may contribute to well-characterised latitude-related differences in autoimmune disease risk." (PMID 33541415, 2021). "VDR knockout mice show increased sensitivity to autoimmune diseases and are more prone to experimentally induced tumours." (PMID 34960140, 2021). "HLA-mediated inflammatory reactions is thought to be linked with CD, HCV and other autoimmune disorders whereby a number of HLAs in this study were mainly regulated by IRF1 and VDR." (PMID 29379596, 2017). "The immunoregulatory role of VD/VDR has been identified in a number of autoimmune diseases, including systemic lupus erythematosus, allograft rejection, autoimmune diabetes mellitus and experimental allergic encephalomyelitis." (PMID 27620138, 2016). "More studies are needed to fully understand the role VDR function and VDR genetic and epigenetic modifications play in preventing autoimmune diseases and dysbiosis." (PMID 28066436, 2016). "One of the most important effects of VDR activation is its ability to increase the innate immune response which is important in the pathogenesis of autoimmune diseases." (PMID 26316435, 2015). "They describe the mechanisms controlling VDR expression and activity, and discuss roles for VDR downregulation in promoting autoimmune diseases or in dampening innate immunity during certain infections." (PMID 26322043, 2015). "Autoimmune disease-reversal by VDR-agonist/antibiotic combinations suggests translational relevance and possible contributions to the long-known but ill-understood links between microbial infections and the etiology of autoimmmunity." (PMID 26322043, 2015). "VDR is one of the most studied genes in relation to T1DM due to its role in T-cell mediated autoimmune diseases." (PMID 26587547, 2015). "Accumulating evidence now supports the observation that a number of autoimmune diseases can be reversed by restoring VDR function (using the VDR agonist olmesartan) along with antibiotics." (PMID 23785369, 2013). "In this model T cells developed normally in thymus but peripheral T cells expressing an inactive VDR were resistant to the inhibitory effect of vitamin D on autoimmune disease development." (PMID 23785369, 2013). "These mice show increased sensitivity to autoimmune diseases, and are more prone to oncogene- and chemocarcinogen-induced tumors illustrating a possible in vivo relation between VDR expression and immune function." (PMID 23785369, 2013). "Due to the importance of T cells in protective immunity and in development of inflammatory and autoimmune disorders, several studies have examined the impact of VDR expression on T cell development, differentiation, and function." (PMID 23785369, 2013). "The protolerogenic properties of VDR agonists render them suitable candidates as immunosuppressants for either autoimmune diseases or graft rejection, as clearly summarized by Mathieu and Adorini, since quite ago." (PMID 23690671, 2013). "Vitamin D, which acts via vitamin D receptor (VDR), possesses immunomodulatory properties and its deficiency has been implicated in the development of autoimmune diseases." (PMID 22654557, 2011). "The vitamin D receptor (VDR) is a ligand inducible transcription factor that has been shown to be an important regulator of many experimental autoimmune diseases including IBD." (PMID 17397543, 2007). "Therefore, an analysis of Italian patients with autoimmune diseases showed that vitamin D receptor (VDR) rs7975232 (T>G) homozygous genotype (GG) was associated with susceptibility to all investigated autoimmune connective tissue disorders." (PMID 39335717, 2024).
autoimmune disease (continued). "In other words, SNPs of the VDR may predispose to acquired vitamin D resistance, which may become manifest during aging and lead to the development of an autoimmune disease, if additional factors accumulate that contribute to an impairment of VDR signaling." (PMID 33897704, 2021). "The importance of the VDR gene is also presented in an in vivo mouse model study where peripheral T lymphocytes with inactive VDRs demonstrated indifference on vitamin D effect in autoimmune disease development." (PMID 33916688, 2021). "The activity of autoimmune diseases is influenced by vitamin-D3 deficiency, and this nonclassical effect of vitamin D is associated with the presence of the vitamin-D receptor (VDR) on numerous cells in the immune system." (PMID 32727130, 2020). "First, it has been observed that certain polymorphisms in the vitamin D receptor (VDR) gene are associated with individual risk of cardiovascular diseases, cancer, and some autoimmune disorders independent of serum 25(OH)D levels." (PMID 32679784, 2020). "Furthermore, according to our study, VDR mRNA expression has been found to be increased in T cells in other autoimmune diseases, such as systemic lupus erythematosus." (PMID 28355272, 2017). "Therefore, understanding the interaction between VDR and gut microbiota is of the utmost importance toward understanding the rise in autoimmune diseases in Western countries." (PMID 28066436, 2016). "Vitamin D receptor (VDR) gene negative mice showed a significantly increased susceptibility to several autoimmune diseases, such as autoimmune encephalomyelitis, autoimmune uveitis and allergic asthma." (PMID 27716192, 2016). "Insights gained from understanding how the VDR pathway is involved in regulating the immune system and changing microbiome diversity may serve as a paradigm for understanding the rise in autoimmune diseases." (PMID 28066436, 2016). "According to our findings, the genotype variations of the VDR gene polymorphisms may be one of the factors in the development of IIM which is a polygenic and multifactorial autoimmune disease." (PMID 25649962, 2015). "These animal studies suggested calcitriol may inhibit autoimmune disease at least in part through a VDR-dependent action on CD4+ T cells to induce IL-10-producing Treg cells." (PMID 25852682, 2015). "The antiproliferative, prodifferentiative, antibacterial, immunomodulatory, and anti-inflammatory properties of synthetic VDR agonists could be exploited to treat a variety of inflammatory and autoimmune diseases." (PMID 26504859, 2015). "However, overall overlap with autoimmune disease regions was still significant suggesting that VDR enrichment of these regions is at least partially independent of preferential binding near immune-related genes." (PMID 23849224, 2013). "Likewise, the effects of changes in serum Ca and Pi due to immobilization, estrogen deficiency (anorexia nervosa, menopause), and physical inactivity on VDR-mediated cellular calcitriol actions and illnesses such as malignancies and autoimmune diseases should be investigated." (PMID 40565034, 2025). "Vitamin D receptor has been found on the surface of almost all cells of the immune system, which may partly explain why abnormal vitamin D metabolism affect the development of some autoimmune diseases." (PMID 38652023, 2024). "Ninety of the differentially methylated VDR peaks overlapped with non-HLA multiple sclerosis risk genes, underlining the potential importance of DNA methylation differences in this latitude-dependent autoimmune disease." (PMID 33541415, 2021). "Furthermore, reversing bacterial-induced VDR dysfunction is key to autoimmune disease." (PMID 34680413, 2021). "In general, little is known about the impact of VDR polymorphisms on the quality of patients’ life since previous studies mostly focused on the prevalence of each polymorphism in autoimmune diseases but not on their relation with the clinical course of the disease." (PMID 32727130, 2020).
autoimmune disease (continued). "Interestingly, the VDR binds to the promoter region of genes involved in the immune system in lymphoblastoid B cell lines, suggesting a role for B cells in the effect of vitamin D on autoimmune diseases." (PMID 28163705, 2016). "Therefore, this review focuses on the role that the interaction between vitamin D, VDR function, and gut microbiome might have on autoimmune diseases in the context of the hygiene hypothesis." (PMID 28066436, 2016). "We have gained insights on how the VDR functions affects inflammation, autophagy, and microbiota composition that could lead to the development of pathogenesis of autoimmune diseases, while confirming the role vitamin D and VDRs have in the context of hygiene hypothesis." (PMID 28066436, 2016). "However, although VDR gene polymorphisms have recently been associated with susceptibility to various autoimmune diseases, there is no comprehensive meta-analysis of VDR gene polymorphisms and the risk of T1DM, and the existing literature is relatively inconsistent." (PMID 40429738, 2025). "Consequently, the genetic variability and epigenetic modifications in the VDR could alter immune homeostasis, significantly impacting the onset and progression of autoimmune diseases, such as rheumatoid arthritis (RA), multiple sclerosis (MS), and Behcet’s disease (BD)." (PMID 38203278, 2023). "Furthermore, the expression of the vitamin D receptor (VDR) on the cell surface hints at this molecule actioning locally in the immune response, findings which are supported by proven relationships between VDR or CYP27B1 gene polymorphisms and several autoimmune diseases’ pathogenesis." (PMID 35208518, 2022). "Vitamin D transmits signals to target cells through the vitamin D receptor (VDR), which is expressed in all immune cells, has been validated to exert a variety of immunomodulatory effects on the prevention of autoimmune diseases." (PMID 31823770, 2019). "Several studies have highlighted the role of methylation in modulating VDR expression in different pathological contexts, mainly in autoimmune diseases, but none of these has concerned OP." (PMID 36980815, 2023). "As there are only very few cases of HVDRR, long-term effects of defective VDR signaling on immune function such as development of autoimmune diseases and control of cancer have not yet been documented." (PMID 23785369, 2013). "In VDR-knockout mice (VDR-KO), VDR has been shown to be non-essential for the development of CD4+, CD8+, and CD4+ FOXP3+ T-cells, though its absence contributes to the development of autoimmune diseases." (PMID 37764988, 2023).
Hypertension (92 papers, 2009 to 2026). The presence of chronic increased pressure in the systemic arterial system. "VDR polymorphisms were differentially distributed across clusters associated with differences in body mass index, hypertension prevalence, and inflammatory status." (PMID 41752094, 2026). "According to the left half of this row, VDR deficiency contributes to hypertension, which aggravates POAG, while elevated VDR protects against retinal ganglion cell loss, which alleviates POAG." (PMID 39684516, 2024). "Two VDR variants; rs228570 (Fok1) and rs1544410 (Bsm1) have been associated with the increased susceptibility to preeclampsia and hypertension among Italians, Chinese and Iranians." (PMID 38814968, 2024). "Our study therefore introduces the possibility of utilizing 25-hydroxy vitamin D deficiency and VDR gene polymorphisms as a biomarker for hypertension." (PMID 38483874, 2024). "For example, it has been found that individuals carrying the VDR SNPs Apa1, Taq1, and Bsm1 genotypes were more likely to be obese, while those with the Fok1 genotype were at an increased risk of heart failure and hypertension." (PMID 38318147, 2024). "Vitamin D receptor (VDR) gene is implicated in hypertension vulnerability due to its role in regulating the renin-angiotensin system (RAS) and blood pressure." (PMID 38483874, 2024). "Beyond essential hypertension (EH), VDR gene polymorphisms have also been linked to other common diseases such as osteoporosis, type 2 diabetes mellitus, and various autoimmune conditions, including multiple sclerosis and systemic lupus erythematosus." (PMID 39715198, 2024). "A FokI variant of the VDR gene is also associated with upregulation of angiotensin II type I receptor and renin gene transcription, leading to hypertension." (PMID 38530345, 2024). "Biological activities of vitamin D are mediated by binding to the VDR, where SNPs can cause changes in arterial BP and contribute to the onset of hypertension." (PMID 36788562, 2023). "A previous GWAS reported that the SNP Bsm I (rs1544410) in the VDR gene is associated with hypertension in Spanish population, systolic BP (SBP) with Bsm I (rs1544410) CC genotype was higher than TC or TT genotypes in men but not in women." (PMID 36788562, 2023). "The population carrying VDR Bsm I AA genotype (OR, 0.69; 95% CI, 0.54–0.89; P = 0.005) had lower susceptibility to hypertension relative to those carrying GA or GG genotype (OR, 1.32; 95% CI, 1.05–1.68; P = 0.02)." (PMID 36788562, 2023). "Mice that lack the vitamin D receptor (VDR) or have a genetic deficiency in the 1-alpha-hydroxylase gene, which is responsible for vitamin D activation, have been shown to develop high renin hypertension and cardiac hypertrophy." (PMID 37760794, 2023). "Prospective studies showed that subjects with low vitamin D level was three times more likely to have hypertension than those with high vitamin D concentrations and also suggested that vitamin D receptor (VDR) polymorphism is associated with hypertension." (PMID 36788562, 2023). "In this regard, in previous investigations, the expression of VDR and genes associated with nephrogenesis in spontaneous hypertension rats (SHR) from week 0 to 8 of life were analyzed." (PMID 36771473, 2023). "Recently, a prospective cohort of American men found suggestive evidence for associations of VDR Bsm I and Fok I polymorphisms with hypertension risk." (PMID 36788562, 2023). "As a result, determining the association of VDR polymorphisms with essential hypertension is expected to aid in the risk assessment for the condition." (PMID 36788562, 2023). "This review identified and analyzed studies that investigated the relationship of VDR (Fok I and Bsm I) polymorphisms with essential hypertension." (PMID 36788562, 2023). "The vitamin D receptor (VDR) gene serves as a good candidate gene for susceptibility to essential hypertension." (PMID 36788562, 2023).